SECTM1 (secreted and transmembrane 1)
Diseases named in the same sentence as SECTM1 in open-access papers:
SECTM1 is named in the same sentence as 27 diseases in open-access papers, as found by Europe PMC text mining. Sharing a sentence is not in itself a finding about the gene and the disease. The quoted sentences say what the papers report.
breast carcinoma (4 papers, 2014 to 2025). "The SECTM1 gene encodes a Golgi-associated secreted and transmembrane protein mainly expressed in leucocytes and breast cancer cell lines." (PMID 38003837, 2023). "The SECTM1 protein level was observed to be increased in many tumours, including breast cancer, leukemia cell lines and melanoma." (PMID 25202906, 2014). "Notably, our findings indicate that the genes upregulated by O-desmethyltramadol in both breast cancer cell lines—IFIT1, GBP4, SECTM1, and OASL—are regulated by interferon." (PMID 40362379, 2025).
melanoma (4 papers, 2014 to 2024). A malignant, usually aggressive tumor composed of atypical, neoplastic melanocytes. "In melanoma, SECTM1 is produced by tumor cells and attracts human monocytes via CD7-mediated activation of the PI3K pathway, leading to cancer progression by attracting monocytes or macrophages." (PMID 36818292, 2023). "Overall, these results suggest SECTM1 is a potential biomarker of benefit to immunotherapy at least in melanoma." (PMID 36818292, 2023). "Further, studies have shown that a ligand for CD7, SECTM1 (secreted and transmembrane protein 1), is highly expressed in many tumors, including melanoma cells." (PMID 29112124, 2017). "The expression of SECTM1 in melanoma cells suggests that SECTM1 may play a role in regulating the tumor microenvironment by inducing monocyte function." (PMID 38164182, 2024). "In addition, cox regression analysis suggested that SECTM1 was a prognosis-related factor in melanoma patients receiving immunotherapy." (PMID 36818292, 2023). "Collectively, these data reveal that SECTM1 could predict the responses to immunotherapy not only in melanoma but also in multiple cancer types." (PMID 36818292, 2023). "It has been revealed that SECTM1 is overexpressed in melanoma tissues." (PMID 36818292, 2023).
pneumococcal pneumonia (3 papers, 2020 to 2023). A febrile disease caused by STREPTOCOCCUS PNEUMONIAE. "The expression of SECTM1 was increased in airway epithelial cells from mice lungs infected with pneumococcal pneumonia." (PMID 38003837, 2023). "SECTM1 is a membrane/secreted airway epithelium-derived protein that was shown to sustain an amplifying loop of neutrophilic inflammation during pneumococcal pneumonia." (PMID 32075873, 2020). "Following pneumococcal pneumonia, conducting airway epithelial cells produce SECTM1 (secreted and transmembrane protein 1), which selectively binds to neutrophils in the infected lung, inducing them to produce CXCL2 and provide a feed-forward loop of neutrophil recruitment." (PMID 36829255, 2023).
gastric cancer (2 papers, 2021 to 2023). A primary or metastatic malignant neoplasm involving the stomach. "In gastric cancer and colorectal cancer, SECTM1 was negatively correlated with MMR genes." (PMID 36818292, 2023).
glioblastoma (2 papers, 2024 to 2025). The most malignant astrocytic tumor (WHO grade IV). "Bioinformatics analysis and Western blotting showed that SECTM1 regulates glioblastoma invasion and EMT-like processes mainly through the TGFβ1/Smad signaling pathway." (PMID 38164182, 2024). "Subsequently, lentivirus knocked down the expression of SECTM1 in glioblastoma cell lines U87 MG and U251 MG." (PMID 38164182, 2024). "Additionally, low SECTM1 has shown potential in suppressing glioblastoma, indicating its promise as a biomarker and therapeutic target for this malignancy." (PMID 39944684, 2025).
glioma (2 papers, 2024). A benign or malignant brain and spinal cord tumor that arises from glial cells (astrocytes, oligodendrocytes, ependymal cells). "ROC curves of prognostic models analyzed in CGGA and TCGA glioma patient data sets showed that high expression of SECTM1 was closely associated with poor prognosis of glioma patients." (PMID 38164182, 2024). "In conclusion, our study found that SECTM1 is highly expressed in gliomas and is associated with survival and poor prognosis of GBM." (PMID 38164182, 2024). "In addition, the high expression of SECTM1 was closely related to glioma grade, IDH mutation and 1p19q deletion." (PMID 38164182, 2024). "We observed that SECTM1 was highly expressed in glioma and found that it was consistent with the analysis of bio information." (PMID 38164182, 2024). "In this study, we found that SECTM1 was highly expressed in glioma and significantly correlated with the survival of glioma patients." (PMID 38164182, 2024). "By regulating the expression of SECTM1 in glioma cell lines, we found that the proliferation, migration and invasiveness of U87MG and U251 MG glioma cells were significantly attenuated after the knockout of SECTM1." (PMID 38164182, 2024). "In summary, the expression of SECTM1 is significantly correlated with the survival of glioma patients." (PMID 38164182, 2024). "The results showed that the expression of SECTM1 in recurrent or secondary gliomas was significantly higher than that in primary gliomas, and the expression of SECTM1 was positively correlated with the malignancy degree of gliomas." (PMID 38164182, 2024). "In low-grade glioma and high-grade glioma, patients with the high SECTM1 expression group had significantly shorter OS than those with the low expression group." (PMID 38164182, 2024). "The expression level of SECTM1 in the IDH wild type glioma was higher than that of the IDH mutant type." (PMID 38164182, 2024). "In the TCGA glioma patient data set, the OS of the SECTM1 group with high expression was significantly shorter than that of the group with low expression, which was consistent with the analysis of the CGGA dataset." (PMID 38164182, 2024). "Methods: qRT-PCR, Western blotting and immunofluorescence were used to detect the expression of SECTM1 in gliomas of different grades and GBM cell lines." (PMID 38164182, 2024). "According to the median expression of SECTM1, glioma patients were divided into a high-expression group and a low-expression group." (PMID 38164182, 2024). "The expression of SECTM1 in different glioma tissue types showed statistically significant differences." (PMID 38164182, 2024). "We detected the expression of SECTM1 in glioma specimens of different clinical grades and glioma cell lines." (PMID 38164182, 2024). "According to the analysis of the CGGA database, SECTM1 is highly expressed in secondary and recurrent gliomas, indicating that SECTM1 may promote the proliferation, invasion and migration of GBM." (PMID 38164182, 2024). "Survival analysis of glioma patients in the CGGA data set showed that the overall survival (OS) of patients with high SECTM1 expression was significantly shorter than that of patients with low SECTM1 expression." (PMID 38164182, 2024). "The role and mechanism of SECTM1 in glioma were elucidated for the first time." (PMID 38164182, 2024). "At the protein level, western blot, immunohistostaining and immunofluorescence staining experiments showed that compared with normal brain tissue, SECTM1 was highly expressed in glioma tissue, and the higher the malignant degree of glioma, the higher the expression of SECTM1." (PMID 38164182, 2024). "The expression level of IDH wild-type SECTM1 in gliomas is higher than that of IDH mutant." (PMID 38164182, 2024). "qPCR results showed that SECTM1 mRNA was highly expressed in glioma tissues." (PMID 38164182, 2024).
glioma (continued). "In vitro experiments have shown that knockdown SECTM1 expression can significantly inhibit the proliferation, invasion and migration of glioma cells, and in vivo experiments have proved that SECTM1 low expression has an inhibitory effect on the growth of glioma." (PMID 38164182, 2024). "Our experiments confirmed that SECTM1 regulates EMT-like processes in GBM cell lines, thereby promoting glioma cell invasion." (PMID 38164182, 2024). "The expression of SECTM1 in WHO grade IV gliomas was significantly higher than that in WHO grade II and III gliomas." (PMID 38164182, 2024). "1p/19q chromosome co-deletion has been considered as a diagnostic and prognostic marker for oligodendroglioma since 199831, and the high expression of SECTM1 in 1p/19q non-codel indicates that SECTM1 expression is significantly correlated with the survival and prognosis of glioma patients." (PMID 38164182, 2024).
atherosclerosis (1 paper, 2014). A disease characterized by the build-up of fatty material and calcium deposition in the arterial wall resulting in partial or complete occlusion of the arterial lumen. "This is not the case for GBP5, Ubd, SectM1, Ifi16, Upp1 and Fam26F, and could therefore represent potential novel biomarkers of atherosclerosis." (PMID 25478796, 2014).
colorectal cancer (1 paper, 2023). A primary or metastatic malignant neoplasm that affects the colon or rectum. "In addition, the correlations between SECTM1 and TMB as well as neoantigen burden were distinctive in different cancers, and SECTM1 showed high correlations with TMB and neoantigen burden in colorectal cancer." (PMID 36818292, 2023).
parasitic infection (1 paper, 2018). "SECTM1 appears to have a role in in cattle immunity as there was a reported 2.73 fold increase in SECTM1 expression in Angus cattle that were resistant to parasitic infection than in those that were susceptible." (PMID 30309336, 2018).
soft tissue sarcoma (1 paper, 2023). A malignant neoplasm arising from muscle tissue, adipose tissue, blood vessels, fibrous tissue, or other supportive tissues excluding the bones. "In soft tissue sarcoma, a signature consisting of SECTM1 and other four immune-related genes, IFIH1, CTSG, STC2, and BIRC5, could predict prognosis and the responses to ICIs23 These evidence further enhanced the correlation of SECTM1 with anti-tumor immunity." (PMID 36818292, 2023).
viral infection (1 paper, 2020). "To further identify the specific IRG that inhibits viral infection, we used siRNAs to knock down the three genes identified above (ADM11, SECTM1, and MYC) in the HCT 116 cell line." (PMID 33292203, 2020).
tumor (13 papers, 2014 to 2026). "SECTM1 expression was notably associated with PD-L1 expression in immune cells (IC) and tumor cells (TC) scores and was increased in inflamed tumors." (PMID 36818292, 2023). "In addition, SECTM1 expression was positively correlated with neoantigen burden and tumor mutation burden (TMB) in the IMvigor210 and GSE176307 cohorts, respectively." (PMID 36818292, 2023). "This review highlights a major shift in our understanding of SECTM1: it acts as a multi-systemic regulator that influences the tumor microenvironment, metabolic homeostasis, and tissue regeneration." (PMID 42233011, 2026). "Integrating bioinformatics and molecular biology experiments, our study highlights the prominent role of SECTM1 in regulating M2-type macrophages within the tumor microenvironment of ESCC." (PMID 39944684, 2025). "The results showed that the proliferation marker Ki67 was significantly reduced in U87-cell-derived tumor tissue with SECTM1 knockdown." (PMID 38164182, 2024). "The results of in vivo imaging indicated that SECTM1 knockdown inhibited tumorigenicity of tumor cells and tumor proliferation and invasion." (PMID 38164182, 2024). "The smallest tumor was found in the sh1 group, and this result intuitively demonstrated that the SECTM1 knockdown inhibited the proliferation of the tumors." (PMID 38164182, 2024). "Staining of brain-frozen sections from in situ tumor-bearing mice showed increased E-cadherin expression and decreased vimentin expression in the SECTM1 knockdown group compared with the NC group." (PMID 38164182, 2024). "Taken together, these data uncover that SECTM1 is a pan-cancer classifier for immuno-hot tumors except for a few tumor types." (PMID 36818292, 2023). "More importantly, the predictive value of tumor-expressed SECTM1 for immunotherapy was also validated using in-house cohorts." (PMID 36818292, 2023). "Overall, tumor-expressed and circulating SECTM1 are both novel and promising biomarkers to predict the immunotherapeutic responses." (PMID 36818292, 2023). "The expression of SECTM1 was significantly enhanced in tumor samples with CR/PR responses compared with that with SD/PD responses." (PMID 36818292, 2023). "Overall, we illustrated the significant function of SECTM1 in mediating anti-tumor immunity and identified SECTM1 as a novel and promising biomarker for the prediction of immunotherapeutic responses in multiple cancers." (PMID 36818292, 2023). "From the previous study of our group, the dysregulated proteins AMBP, KLK3, LMAN2, and TTR were found dysregulated in urine and tumor tissue from PCa patients, while SECTM1 was only found in urine from PCa patients, and CDH1 and EFEMP1 were only in PCa tissue." (PMID 35454907, 2022). "Integrating the findings from bioinformatics analysis and cell experimental results, we elucidated that overexpression of SECTM1 may promote the polarization of macrophages from M0 to M2 and promote M2 macrophages chemotaxis to tumor cells." (PMID 39944684, 2025). "In vivo experiments also demonstrated that SECTM1 knockdown inhibited tumor growth." (PMID 38164182, 2024). "Moreover, SECTM1 was negatively correlated with tumor purity but positively correlated with TILs levels in most cancer types." (PMID 36818292, 2023). "Moreover, analysis of in-house immunotherapy cohorts suggested both tumor-expressed and circulating SECTM1 are promising biomarkers to predict therapeutic responses." (PMID 36818292, 2023). "Given that CAR T cells disrupted for CD7 retain potent functional activity, it appears that CD7 signalling, and by proxy SECTM1 activity, may be redundant for anti-tumour function." (PMID 34035409, 2021). "Moreover, we checked the correlations between SECTM1 and immunomodulators expression, which were associated with features of tumor immune microenvironment (TIME) and the responses to immunotherapy, and the results showed that SECTM1 was positively correlated with most immunomodulators." (PMID 36818292, 2023).
tumor (continued). "Thus, we speculate whether SECTM1 is an oncogene or a tumor suppressor dependent on the composition of immune cell types in the TIME, since multiple immune cells could express CD7, such as T cells, NK cells, and monocytes." (PMID 36818292, 2023). "The results indicated that SECTM1 knockdown inhibited the EMT process, thereby suppressing tumor invasion." (PMID 38164182, 2024). "An abridged list contains 23 hypermethylated genes and 4 hypomethylated genes (CACNA2D4;LRTM2, ESPNL, SECTM1, PCDH8) for AA tumor samples; whereas, 29 hypermethylated genes and 1 hypomethylated gene (BRSK2) are listed for the CA tumor samples." (PMID 27111221, 2016). "SECTM1 is upregulated by IFN-γ (interferon-gamma)/STAT1 (signal transducer and activator of transcription 1) signaling in immuno-hot tumors, further highlighting its role in tumor-immune interactions." (PMID 40362379, 2025). "We found that compared with the negative control SECTM1-NC, the tumor with SECTM1 knockdown was significantly smaller and the tumor growth was slower, and the higher the degree of SECTM1 knockdown, the slower the tumor growth." (PMID 38164182, 2024). "However, the functional role of SECTM1 in human cancers and its correlations with anti-tumor immunity have not been investigated." (PMID 36818292, 2023). "Although an association between SECTM1 and STS has not yet been identified, our study provides insight into the tumor-associated immune mechanisms of STS, and the overexpression of SECTM1 may be important in STS development." (PMID 32873319, 2020). "To verify whether SECTM1 was involved in the EMT process in vivo, we performed immunofluorescence staining for EMT markers (E-cadherin: green, Vimentin: red) on brain-frozen sections of in situ tumor-bearing mice and tumor tissue frozen sections of subcutaneous tumor-bearing mice, respectively." (PMID 38164182, 2024).
cancer (9 papers, 2014 to 2026). A tumor composed of atypical neoplastic, often pleomorphic cells that invade other tissues. "We systematically delineate the molecular mechanisms by which SECTM1 governs immune cell migration and activation across diverse pathologies, including cancer, cardiovascular disorders, and neurodegenerative diseases." (PMID 42233011, 2026). "From the prognostic model, we selected SECTM1 gene for further investigation to its potential pro-cancer effects." (PMID 39944684, 2025). "In this research, more than ten public and in-house cohorts were used to explore the predictive value and immunological correlations of secreted and transmembrane 1 (SECTM1) in cancers." (PMID 36818292, 2023). "First, as a less-focused immune-related molecule, the biological function of SECTM1 in cancer has not been well understood." (PMID 36818292, 2023). "To further verify the predictive value of SECTM1 for immunotherapy in human cancers, we obtained more public datasets." (PMID 36818292, 2023). "Except for CHOL, SECTM1 was positively correlated with the expression levels of these immunomodulators in almost all cancer types." (PMID 36818292, 2023). "Moreover, SECTM1 has been identified as a potential predictive biomarker for the response to immunotherapy in various types of cancer, showing upregulation in immune-hot tumors and sensitivity to the IFN-γ/STAT1 signaling pathway." (PMID 39944684, 2025). "Furthermore, its overexpression promoted macrophage polarization towards the M2-like phenotype and promoted the migration of M2-like macrophage cells and C-C Motif Chemokine Ligand 5 (CCL5) was the key mediator in the pro-cancer effect of SECTM1." (PMID 39944684, 2025). "Additionally, SECTM1 expression has been found to be elevated in tumors from patients who exhibit strong immunotherapeutic responses across multiple cancer types." (PMID 40362379, 2025). "In addition, the immunological correlations of SECTM1 in pan-cancer were systematically analyzed using The Cancer Genome Atlas (TCGA) dataset and validated using four independent in-house cohorts." (PMID 36818292, 2023). "In this research, we aimed to explore the immunological correlations of SECTM1 in human cancer." (PMID 36818292, 2023). "Next, the immunological correlations of SECTM1 in pan-cancer were explored using the TCGA dataset." (PMID 36818292, 2023). "Overall, this study reveals that SECTM1 is a biomarker of benefit to ICIs in cancer patients." (PMID 36818292, 2023). "This suggests that SECTM1’s pro-cancer effect in ESCC may be related to the immune mechanism." (PMID 39944684, 2025). "In addition, SECTM1 was immuno-correlated in pan-cancer and enhanced in immuno-hot tumors." (PMID 36818292, 2023). "Although the available evidence indicates that SECTM1 is an immunostimulator and activates multiple immune cells via CD7-dependent manner, SECTM1 still has a cancer-promoting effect in tumors." (PMID 36818292, 2023). "The urine proteome profile of PCa and cancer-free subjects was analyzed by two software packages and 18 dysregulated proteins, of which 5 (TTR, EFEMP1, CDH1, SECTM1, KLK3) common to both software, were found." (PMID 35454907, 2022). "Changes in the expression of SECTM1 and OLFM4, as well as in the activity of TGR5, play a role in the immunological tolerance to cancer cells and the colonization of tissues by bacteria." (PMID 30944407, 2019).
SECTM1 also shares sentences with these, for which no sentence is quoted: prostate carcinoma (2 papers); cardiovascular disorder (1); colitis (1); diabetic kidney disease (1); dilated cardiomyopathy (1); endometrial cancer (1); esophageal squamous cell carcinoma (1); heart failure (1); hypertrophic cardiomyopathy (1); kidney malignant tumours (1); leukemia (1); neurodegenerative disease (1); oligodendroglioma (1); stomach cancer (1).